ARMC6 (armadillo repeat containing 6)
Synonyms: MGC19595; R30923_1
Tractability: PROTAC: ubiquitination databases record sites on it; its protein half-life has been measured.
Gene: Protein-coding gene on chromosome 19 (19,033,575 to 19,060,311, forward strand). Ensembl gene ENSG00000105676.
Subcellular location (Human Protein Atlas): Cytosol
Gene Ontology:
Biological process: hematopoietic progenitor cell differentiation
Cellular component: cytosol
Genetic constraint (gnomAD): Loss-of-function variants: 43 observed, 49.87 expected, observed/expected ratio (o/e) 0.86, 90% interval 0.68 to 1.11. The upper end of that interval is the gene's LOEUF score, 1.11, which puts it in group 4 of 6, group 1 being the genes least tolerant of losing a copy. Missense variants: 627 observed, 702.67 expected, observed/expected ratio (o/e) 0.89, 90% interval 0.83 to 0.95. Synonymous variants: 262 observed, 300.27 expected, observed/expected ratio (o/e) 0.87, 90% interval 0.79 to 0.97.
Homologues: Orthologues: chimpanzee ARMC6 (98% identical), pig ARMC6 (81% identical), macaque ARMC6 (80% identical), dog ARMC6 (80% identical), mouse Armc6 (78% identical), rat Armc6 (77% identical), guinea pig ARMC6 (75% identical), tropical clawed frog armc6 (62% identical), rabbit ARMC6 (61% identical), zebrafish ARMC6 (59% identical), Drosophila melanogaster CG5721 (30% identical).
Diseases named in the same sentence as ARMC6 in open-access papers:
ARMC6 is named in the same sentence as 4 diseases in open-access papers, as found by Europe PMC text mining. Sharing a sentence is not in itself a finding about the gene and the disease. The quoted sentences say what the papers report.
neuroblastoma (2 papers, 2020 to 2021). Neuroblastoma (NB) is the most common solid, extracranial childhood tumor. "Interestingly, six genes ARMC6, DCTPP1, EIF4G1, ELOVL6, FBL and PRMT1 were associated with the clinical overall survival of neuroblastoma in both TARGET and GSE85047 datasets." (PMID 32593299, 2020). "ARMC6 is the target gene of MYCN and indicates a poor prognosis for patients with neuroblastoma (NB)." (PMID 34912852, 2021). "The present study suggested new prognostic markers of ARMC6, DCTPP1, EIF4G1, ELOVL6 and FBL in neuroblastoma and highlighted the combinational prognostic significance of MYCN amplification and EIF4G1 expression in patients with neuroblastoma." (PMID 32593299, 2020). "Therefore, functions and prognosis of ARMC6, DCTPP1, EIF4G1, ELOVL6 and FBL in neuroblastoma should be further studied." (PMID 32593299, 2020). "However, the functions and prognosis of ARMC6, DCTPP1, EIF4G1, ELOVL6 and FBL in neuroblastoma were not reported." (PMID 32593299, 2020).
pancreatic cancer (1 paper, 2019). "Armc6 is highly conserved with Gene Ontology (GO) that suggests involvement in hematopoietic progenitor cell differentiation (GO:0002244) and in pancreatic cancer." (PMID 31694869, 2019).
nervous system disorder (1 paper, 2022). A non-neoplastic or neoplastic disorder that affects the brain, spinal cord, or peripheral nerves. "On the other hand, the ARMC proteins including ARMC4, ARMC5, ARMC6, ARMC7, ARMC8, ARMC10, and ARMCX3 regulate the Wnt signaling pathway leading to specific nervous system disorders." (PMID 36553564, 2022).
ARMC6 also shares sentences with these, for which no sentence is quoted: Hepatic steatosis (1 paper).